AARSD1 (alanyl-tRNA synthetase domain containing 1)
Description:
Functions in trans to edit the amino acid moiety from incorrectly charged tRNA(Ala).
Synonyms: MGC2744; AlaXp
Gene: Protein-coding gene on chromosome 17 (42,950,431 to 42,964,498, reverse strand). Ensembl gene ENSG00000266967.
Subcellular location: Cytoplasm
Subcellular location (Human Protein Atlas): Cytosol; Nuclear membrane
Gene Ontology:
Molecular function: Ser-tRNA(Ala) deacylase activity; alanine-tRNA ligase activity; aminoacyl-tRNA deacylase activity; aminoacyl-tRNA ligase activity; ATP binding; nucleic acid binding; nucleotide binding
Biological process: regulation of translational fidelity; alanyl-tRNA aminoacylation; aminoacyl-tRNA metabolism involved in translational fidelity; tRNA aminoacylation
Cellular component: nucleus; cytoplasm
Genetic constraint (gnomAD): Loss-of-function variants: 46 observed, 52.42 expected, observed/expected ratio (o/e) 0.88, 90% interval 0.69 to 1.12. The upper end of that interval is the gene's LOEUF score, 1.12, which puts it in group 4 of 6, group 1 being the genes least tolerant of losing a copy. Missense variants: 511 observed, 552.58 expected, observed/expected ratio (o/e) 0.92, 90% interval 0.86 to 1. Synonymous variants: 189 observed, 207.18 expected, observed/expected ratio (o/e) 0.91, 90% interval 0.81 to 1.03.
Homologues: Orthologues: chimpanzee PTGES3L (97% identical), macaque AARSD1 (94% identical), dog AARSD1 (91% identical), pig AARSD1 (91% identical), mouse Aarsd1 (90% identical), rabbit AARSD1 (89% identical), guinea pig AARSD1 (80% identical), rat Aarsd1 (69% identical), tropical clawed frog aarsd1 (64% identical), zebrafish aarsd1 (63% identical), Drosophila melanogaster CG10802 (45% identical). Paralogues in human: AARS1 (22% identical), AARS2 (22% identical).
Diseases named in the same sentence as AARSD1 in open-access papers:
AARSD1 is named in the same sentence as 5 diseases in open-access papers, as found by Europe PMC text mining. Sharing a sentence is not in itself a finding about the gene and the disease. The quoted sentences say what the papers report.
Headache (1 paper, 2022). Cephalgia, or pain sensed in various parts of the head, not confined to the area of distribution of any nerve. "Of the genes at these loci, six (FAF1, TMX2-CTNND1, AARSD1, PLCD3, ZNF652, and C20orf203; headache-TSH) and six (HMGB1P45, RPL30P1, ZNF462, TMX2-CTNND1, ITPK1, SECISBP2L; headache-fT4) were significant in our gene-based analysis (pFisher’s combined p-value < 2.09 × 10−6)." (PMID 36672757, 2022).
Renal insufficiency (1 paper, 2025). A reduction in the level of performance of the kidneys in areas of function comprising the concentration of urine, removal of wastes, the maintenance of electrolyte balance, homeostasis of blood pressure, and calcium metabolism. "Finally, for Renal insufficiency, 3,041 genes and 363 related proteins were identified, with 72 gene-protein overlapping targets such as ADAM15, CD86, and AARSD1." (PMID 41340073, 2025).
AARSD1 also shares sentences with these, for which no sentence is quoted: glioma (2 papers); cardiovascular diseases (1); liver cancer (1).